IL1B (interleukin 1 beta)
Diseases named in the same sentence as IL1B in open-access papers (continued):
Sharing a sentence is not in itself a finding about the gene and the disease.
pulmonary fibrosis (continued). "The Net-M5 detected genes involved in lung fibrosis (CXCL8 and IL1B), VEGFA-VEGFR2 signaling (NR4A1 and CBL), and TGF-β signaling (JUNB and ATF3)." (PMID 38259488, 2023). "The mechanism by which NLRP3 contributes to the development of lung fibrosis begins with the activation of toll-like receptor (TLR) and NF-κB, providing a priming signal that induces the upregulation of pro-IL-1β and inflammasome components." (PMID 38003456, 2023). "In experimental models of lung fibrosis, mice treated with BLM displayed increased IL-1β production, inflammation, remodeling, and fibrosis in a manner dependent on IL-1R1/MyD88 signaling." (PMID 37849737, 2023). "The inflammatory activities of IL-1β, IL-6, MPO, TGF-β1, and TNF-α in the lung tissues of both normal control rats and BLM-induced lung fibrosis rat models were determined." (PMID 35268069, 2022). "Their vivo study demonstrated that pre-treatment with GW4869 decreased lung fibrosis and the expression of TNF-α, IL-1β, and IL-6 in silicosis model." (PMID 35677105, 2022). "In this study, hMIKO-1 administration suppressed pulmonary fibrosis and the expression of F4/80, inflammatory cytokines (TNF-α, IL-6, and IL-1β), and fibrotic factors in the lungs of BLM-ILD mice." (PMID 36077067, 2022). "Triptolide inhibited of IKKβ/NF-κB-mediated lysyl oxidase (LOX) production to reduce profibrotic IL-1β, IL-13 and TGF-β to diminish radiation-induced pulmonary fibrosis, and to improve mouse survival following radiation." (PMID 36700235, 2022). "The cell count and cytokines (IL-1β, IL-6, and IL-8) of bronchoalveolar lavage (BAL) fluid were also increased in bleomycin-induced lung fibrosis in rat." (PMID 34742261, 2021). "According to the existing studies, the development of pulmonary fibrosis in the patients with SARS-CoV-2 infection is accompanied by the increased expression of cytokines such as TGF-β, TNF-α, IL-1β, IL-6 and IL-13." (PMID 34876129, 2021). "More importantly, an in vivo study demonstrated that pre‐treatment with GW4869 decreased lung fibrosis and the expression of TNF‐α, IL‐1β and IL‐6 in BALF." (PMID 33834616, 2021). "Liposomal quercetin was demonstrated to attenuate bleomycin-induced pulmonary fibrosis in vivo by the suppression of inflammatory cytokines (TNF-α, IL-1β, and IL-6) and the diminish of total cells and macrophage counts in BALF." (PMID 35126133, 2021). "Anaerobic glycolysis and aerobic glycolysis are also thought to promote the formation of pulmonary fibrosis by activating NLRP3 or AIM2 to induce macrophage pyroptosis and by mediating the transcription of IL-1β through the HIF-α pathway, respectively." (PMID 34944017, 2021). "In the BLM-induced pulmonary fibrosis model mice and BLM-stimulated PAECs, TA293 suppressed the expression of Il1b and Il18 mRNAs, but mitoTA293 increased their expression levels." (PMID 34573030, 2021). "Our analysis showed that eight genes (CSF2, CSF3, CXCL2, CXCL8, IL1B, IL6, MMP9, and TNF) are significantly overlapping with the lung fibrosis pathway with p-value 9.35e-11." (PMID 33362771, 2020). "Previous studies have indicated that multiple cytokines, including TGF-β1, IL-1β, TNF-α, IL-17, IL-27, IL-13, and IL-32, are overexpressed in pulmonary fibrosis." (PMID 33097029, 2020). "An ELISA of the whole lung extracts showed that interleukin-1 beta (IL-1β) and macrophage inflammatory protein-2 (MIP-2) levels were significantly higher in the pulmonary fibrosis model group than in the control group seven days after bleomycin injection." (PMID 32630825, 2020). "The secretion of cytokines, including IL-1β, IL-6, TNF-α, and MCP-1, plays a certain role in the pathogenesis of pulmonary fibrosis." (PMID 31947943, 2020). "In the absence of FOXM1, the p38 MAPK pathway is activated in macrophages leading to production of pro-fibrotic mediators IL-1β, IL-6 and TNF-α that directly stimulate fibroblast activation and survival, exacerbating pulmonary fibrosis." (PMID 32271749, 2020).
pulmonary fibrosis (continued). "Improved lung function and reduced alveolar collapse.Reduced lung inflammation and lung fibrosis.Reduced TNF-α, IL-1β, KC, and TGF-β levels.Reduced apoptosis in the lung, kidney, and liver." (PMID 32519302, 2020). "These cells secrete pro-inflammatory and pro-fibrotic cytokines and chemokines, including IL-1β, IL-6, TNF-α, and MCP-1, which influence the pathogenesis of pulmonary fibrosis." (PMID 30250465, 2018). "To evaluate the anti-inflammatory and anti-fibrotic effects of CNP against BLM-induced lung fibrosis in periostin-CNP Tg mice, we analyzed the mRNA expression changes of IL-1β, IL-6, bFGF, TGF-β, TIMP1, and collagen 1A." (PMID 26895702, 2016). "αB-crystallin knockout mice were protected against bleomycin-induced pulmonary fibrosis and fibrosis induced by over-expression of TGF-β or IL-1β." (PMID 27144281, 2016). "IL-1β overexpression in rodent lung induced the upregulation of TGF-β1, a major pro-fibrotic growth factor, and lung fibrosis." (PMID 27894300, 2016). "Given the broad and critical roles of IL-1β, it is believed that inflammasome activation plays an important role in myofibroblast formation and function in CNT-induced lung fibrosis." (PMID 27814727, 2016). "In patients with idiopathic pulmonary fibrosis (IPF), IL-17A cooperates with and cross-regulates IL-1β, and the interaction of these cytokines contributes critically to neutrophil recruitment and lung fibrosis and possibly to liver fibrosis." (PMID 25590646, 2015). "In the experimental mouse model of pulmonary fibrosis utilized in this study, BLM induces pneumonitis, which leads to fibrotic changes resulting from increased IL‐1β and TGF‐β1 production." (PMID 26660549, 2015). "Increased levels of IL-1β and IL-1α have been described to be involved in the pathogenesis of ARDS and subsequent pulmonary fibrosis." (PMID 26303896, 2015). "At the model of partially reversible pulmonary fibrosis by ELISA we evaluated levels of cytokines (TGF-β, IL-1β and TNF-α) in the lung parenchyma and serum on the 3rd after BLM treatment." (PMID 25927611, 2015). "The data showed that TNF-α and IL-1β dramatically up-regulated not only in the acute phase of LPS-induced model but also 8 weeks later in the BLM-induced pulmonary fibrosis." (PMID 25465226, 2014). "IL-1β and MCP-1 are considered to promote pulmonary fibrosis by triggering the activation and proliferation of fibroblasts and to stimulate collagen production." (PMID 25561223, 2014). "It is well known that increased expression levels of the proinflammatory cytokines IL-6, IL-1β and TNF-α and decreased expression levels of the anti-fibrotic cytokine IFN-γ are involved in the pathogenesis and progression of pulmonary fibrosis." (PMID 25092105, 2014). "The pivotal function of IL-1β and NALP3 inflammasome in the development of lung fibrosis had been proved before." (PMID 22615967, 2012). "However, after treatment with LP03, the concentrations of TNF-α, IL-6, and IL-1β were notably reduced, highlighting the protective effect of LP03 against the inflammatory response in BLM-induced pulmonary fibrosis." (PMID 40994978, 2025). "The inhibition of NLRP3-mediated IL-1β production suggests that LA1 could be repurposed to treat NLRP3-mediated inflammatory diseases, such as lung fibrosis." (PMID 40114914, 2025). "IL-1β is a proinflammatory cytokine that is known to induce epithelial to mesenchymal transition (EMT) in A549 cell line during chronic inflammation and ultimately leads to pulmonary fibrosis and progression of cancer." (PMID 39120378, 2024). "The levels of caspase-11, cleaved GSDMD, and IL-1β levels were significantly increased, which contributed to pulmonary inflammation in BLM-stimulated human and rat lung epithelial cells, as well as in BLM-induced pulmonary fibrosis mice." (PMID 39795884, 2024).
pulmonary fibrosis (continued). "Lastly, several cytokines involved in TH2 cell recruitment and fibrosis (IL-6, eotaxin, PDGF-ββ, IL-10, IL-1β) were released from macrophages in vitro and correlated with in vivo BAL response, which aligns with KE4 (TH2 cell activation) in the lung fibrosis AOP." (PMID 38509617, 2024). "JWH133 activated CB2R regulating the inflammatory response, and subsequently reduced pulmonary fibrosis in mice.The ELISA results showed significantly higher levels of inflammatory markers TNF-α, IL-6, and IL-1β in the serum of the BLM group, which decreased after the administration of JWH133." (PMID 37957604, 2023). "Finally, the results that increased IL‐1β and TGF‐β1 in AT2 pneumocytes and epithelial cells either in old mice or in mice exposed to hypoxia is inhibited in arg‐ii−/− animals, reinforce our conclusion and may represent an explanantion of hypoxia‐associated lung fibrosis." (PMID 36794355, 2023). "Indeed, one main etiology of pulmonary fibrosis is acute and/or chronic inflammation via the release of lung proinflammatory cytokines and chemokines (such as TNF-α, IL-1β, IL-6, and IL-8) along with NF-κB." (PMID 36830999, 2023). "In mice with graphitized multi-walled carbon nanotube (GMWCNT)-induced pulmonary fibrosis, high expression of cGAS, STING, IFN-β, NF-κB, IL-1β, and TGF-β1 indicates the induction of an inflammatory response through activation of the cGAS-STING signaling pathway." (PMID 37965345, 2023). "Further, it has also been reported that TLR signaling could trigger the pathology of pulmonary fibrosis by increasing the production and release of cytokines such as IL-6, TNF-α, and IL-1β." (PMID 36232756, 2022). "Compared with apoptosis, an immune-silent programmed death, pyroptosis could release IL1β and IL18 which could interact with macrophages and fibroblast and therefore have more a strong effects on mechanism of pulmonary fibrosis." (PMID 36033388, 2022). "Another research indicated that asbestos and silica could stimulate NLRP3-dominant secretion of IL-1β in THP-1 macrophages, which may trigger pulmonary fibrosis and diseases." (PMID 35415237, 2022). "All these indicate that TGF-β, TNF-α, IL-1β, IL-6, IL-13, ACE2 and autophagy inhibition may be the key factors in pulmonary fibrosis induced by SARS-CoV-2." (PMID 34876129, 2021). "C/EBPβ also plays an important role in experimental lung fibrosis, as demonstrated by C/EBPβ null mice that developed less lung fibrosis after bleomycin injury due to the reduced production of lung pro-inflammatory cytokines TGFβ1, TNF-α, and IL-1β, and myofibroblast differentiation." (PMID 34207528, 2021). "Following bleomycin-induced lung injury, Il11−/− mice are protected from pulmonary fibrosis and exhibit lesser ERK, STAT3 and NF-kB activation, reduced Il1b, Timp1, Ccl2 and diminished IL6 expression, both at baseline and after injury: placing Il11 activity upstream of IL6 in this model." (PMID 34239012, 2021). "While there has not been a trial evaluating the effect of neutralizing IL-1β in IPF, mice deficient in IL-1R1 are protected and developed attenuated bleomycin-induced pulmonary fibrosis." (PMID 34258628, 2021). "In this experiment, we found that Yifei decoction combined with MitoQ could significantly reduce the expression of IL-6, IL-1β, TNF-α, and MDA and increase the activity of GSH-Px and SOD in lung tissue of rats with pulmonary fibrosis induced by bleomycin." (PMID 34135982, 2021). "It has been shown that macrophages, and inflammatory mediators, including IL-1β and TNF-α, could contribute to exacerbating lung fibrosis." (PMID 34399790, 2021). "The successful establishment of a mouse model with T2DM‐associated PTB was confirmed as inflammatory cell infiltration and increased pulmonary fibrosis, as well as increased production of pro‐inflammatory factors including TNF‐α, IL‐6 and IL‐1β in mouse lung tissues." (PMID 33089914, 2020).
pulmonary fibrosis (continued). "Additionally, TGF-β1 also modulates several signaling pathways, including activation of Smad, TNF-α and IL-1β, inhibition of AMPK activity, which induces EC injury and extracellular matrix production, thus promoting the progression of pulmonary fibrosis." (PMID 31611754, 2019). "The expression of miR-155 in human lung fibroblasts was upregulated by TNF-α and IL-1β and downregulated by TGF-β1; miR-155, which might target keratinocyte growth factor, promoted migration of fibroblasts and enhanced pulmonary fibrosis." (PMID 31013581, 2019). "An increase in IL-1β levels might stimulate epithelial-mesenchymal transition and myofibroblast activation through a TGF-β1-mediated mechanism, thus leading to lung fibrosis." (PMID 29126438, 2017). "To determine whether NNAV rendered the protection by inhibiting inflammatory process, we analyzed the serum inflammatory cytokines IL-1β and TNF-α in LPS-induced (acute phase) and BLM-induced pulmonary fibrosis." (PMID 25465226, 2014). "NNAV decreased IL-1β and TNF-α levels in serum in both pulmonary fibrosis models." (PMID 25465226, 2014). "In addition to IFN-γ, the classic proinflammatory cytokines IL-1β and TNF-α are increased in V2O5-induced lung fibrosis in mice and rats." (PMID 20738867, 2010). "Ample evidence supports that SiO2 activates inflammatory cytokines such as IL-1β, IL-6, TGF-β, TNF-α, growth factors, and CCL and promotes pulmonary fibrosis, suggesting that increased inflammatory cytokine levels may be used as typical biomarkers for the clinical diagnosis of silicosis." (PMID 38515835, 2024). "PDE is suggested to contribute to pulmonary fibrosis, and there is a report stating that the PDE4B inhibitor suppress pulmonary fibrosis in mice and HLFs from patients with idiopathic pulmonary fibrosis (IPF) by inhibiting the TGFβ signaling pathway and suppressing cell proliferation via IL-1β." (PMID 39684311, 2024). "In this study, the administration of hESC-MSC-IMRCs or hESC-MSC-IMRC-CM exhibited an ability to suppress TNF-α, IL-1β, and IL-6 release in lung tissues of BLM-challenged mice, suggesting that hESC-MSC-IMRCs or hESC-MSC-IMRC-CM could mitigate pulmonary fibrosis by relieving inflammatory responses." (PMID 36830999, 2023). "Thus, using this model, in this study we investigated the effects of NXC736 on the regulation of EMT and pulmonary fibrosis by inhibiting the signaling pathways of NLRP3 and IL-1β in RILF, with the goal of assessing its potential as a pulmonary fibrosis inhibitory drug." (PMID 38003456, 2023). "Reduced the levels of caspase-3, IL-1β, TNF-α, TGF-β, HYP, 3-NT, and 4-HNE; increased the levels of Nrf2, HO−1, NQO1, SOD1, and CAT; alleviated BLM-induced alveolar epithelial cell apoptosis, alveolitis, collagen accumulation, lung oxidative stress, and lung fibrosis." (PMID 36139759, 2022). "Downregulated expression of TNF-α, IL-1β, IL-6 and IL-10 proteins indicated that AD-MSCs can also protect the lungs from injury and fibrosis through an anti-inflammatory process, which was consistent with ample experimental evidence in MSC-treated pulmonary fibrosis." (PMID 29673394, 2018). "Indeed, in our experimental model of bleomycin-induced pulmonary fibrosis (measured by collagen deposition around the airways), we observed that IL-1β, rather than IL-18, as observed in humans, is upregulated in mRNA levels after bleomycin treatment." (PMID 29675024, 2018). "However, animal studies have shown that they could promote the production of pro-fibrogenic cytokines and growth factors (IL-1β, TGF-β and PDGF-AA, etc.)that may lead to lung fibrosis." (PMID 28649460, 2016). "Notably, a direct interaction between vimentin and NLRP3 was demonstrated as well as an important role for macrophages based upon the finding that bone marrow chimeric mice lacking vimentin have decreased lung fibrosis as well as levels of caspase-1 and IL-1β." (PMID 26370974, 2015).
pulmonary fibrosis (continued). "In addition, when DMY was used to interfere with fibrotic lung injury induced by methotrexate, it was found through lung histopathological examination that DMY could reduce the levels of NF-κB, IL-1β and TGF-β1 to inhibit lung inflammation and pulmonary fibrosis." (PMID 38625956, 2024). "While IL-1β, TNF-α and IL-4, known for their implication in the extension of lung fibrosis, had no or limited effect on Cat K expression, both concentrations of TGF-β1 (1 and 10 ng/ml) reduced Cat K expression." (PMID 16045809, 2005). "Of note, concerning systemic involvement in HOCl-SSc, iNOS−/−-MSC were not able to reduce fibrotic markers such as collagen 1 and α-SMA and inflammatory cytokines (IL-1β and IL-6) in lung tissue, while WT-MSC had a positive impact on pulmonary fibrosis in this model (data not shown)." (PMID 30622540, 2018).